KHDC4 (KH domain containing 4, pre-mRNA splicing factor)
Description:
RNA-binding protein involved in pre-mRNA splicing. Interacts with the PRP19C/Prp19 complex/NTC/Nineteen complex which is part of the spliceosome. Involved in regulating splice site selection. Binds preferentially RNA with A/C rich sequences and poly-C stretches.
Synonyms: BLOM7; KIAA0907; SNORA80EHG
Tractability: No criterion of Open Targets' tractability assessment is met for any kind of drug.
Gene: Protein-coding gene on chromosome 1 (155,913,043 to 155,934,413, reverse strand). Ensembl gene ENSG00000132680.
Subcellular location: Nucleus; Cytoplasm
Subcellular location (Human Protein Atlas): Nucleoplasm
Gene Ontology:
Molecular function: protein binding; RNA binding
Biological process: mRNA splice site recognition
Cellular component: cytoplasm; nucleoplasm; nucleus; spliceosomal complex
Genetic constraint (gnomAD): Loss-of-function variants: 16 observed, 59.06 expected, observed/expected ratio (o/e) 0.27, 90% interval 0.18 to 0.41. The upper end of that interval is the gene's LOEUF score, 0.41, which puts it in group 1 of 6, group 1 being the genes least tolerant of losing a copy. Missense variants: 538 observed, 662.26 expected, observed/expected ratio (o/e) 0.81, 90% interval 0.76 to 0.87. Synonymous variants: 220 observed, 233.65 expected, observed/expected ratio (o/e) 0.94, 90% interval 0.84 to 1.05.
Homologues: Orthologues: chimpanzee KHDC4 (100% identical), macaque KHDC4 (100% identical), pig KHDC4 (99% identical), rabbit KHDC4 (98% identical), guinea pig KHDC4 (97% identical), rat Khdc4 (97% identical), dog KHDC4 (96% identical), mouse Khdc4 (95% identical), tropical clawed frog khdc4 (71% identical), zebrafish khdc4 (56% identical).
Diseases named in the same sentence as KHDC4 in open-access papers:
KHDC4 is named in the same sentence as 7 diseases in open-access papers, as found by Europe PMC text mining. Sharing a sentence is not in itself a finding about the gene and the disease. The quoted sentences say what the papers report.
colorectal cancer (1 paper, 2025). A primary or metastatic malignant neoplasm that affects the colon or rectum. "In colorectal cancer, an increase in KHDC4 was associated with GALC expression in patients treated with oxaliplatin and capecitabine." (PMID 40560737, 2025). "An increased level of KHDC4 has been observed in colorectal cancer tissues and is correlated with a worse survival rate." (PMID 40560737, 2025).
lymph node metastasis (1 paper, 2025). "The elevated levels of KHDC4 in late-stage and lymph node metastasis are positively correlated with poorer overall survival and disease-free survival rates in PCa patients." (PMID 40560737, 2025). "Regarding lymph node metastasis, in pathologic N, KHDC4 exhibited a positive correlation with TRAF2 (Spearman’s correlation = 0.3481, p < 0.0001)." (PMID 40560737, 2025).
melanoma (1 paper, 2025). A malignant, usually aggressive tumor composed of atypical, neoplastic melanocytes. "In melanoma cells, the elevated genes included MAP2K7, RIOK1, GOPC, KHDC4 and PDPK1, which may be associated with stress/drug resistance, protein synthesis, and the regulation of cellular migration." (PMID 41383633, 2025).
prostate carcinoma (1 paper, 2025). A carcinoma that arises from epithelial cells of the prostate gland. "Notably, the androgen receptor-independent transactivation of KHDC4 and TRAF2 by E2F4 was demonstrated using multiple prostate cancer cell lines and further validated through clinically relevant transcriptome datasets." (PMID 40560737, 2025). "Moreover, analysis of human prostate cancer datasets from TCGA (Cell, Firehose Legacy, and PanCancer) did not reveal a significant positive correlation between KHDC4 or TRAF2 and androgen receptor expression." (PMID 40560737, 2025).
cancer (3 papers, 2020 to 2025). A tumor composed of atypical neoplastic, often pleomorphic cells that invade other tissues. "From a pan-cancer perspective, KHDC4 was found to be increased in multiple cancer types and correlated with worse prognosis values, including PCa." (PMID 40560737, 2025). "Moreover, the downstream effectors of KHDC4 and TRAF2 were observed to be positively correlated with E2F4, suggesting that E2F4, in addition to affecting KHDC4 and TRAF2 directly, indirectly influences their downstream regulators to participate in cancer malignancy." (PMID 40560737, 2025).
tumor (2 papers, 2021 to 2025). "Through a KHDC4-based molecular simulated model, abnormal elevation of KHDC4 levels was implicated in participating in epithelial proliferation and repair-related functions in tumor cells." (PMID 40560737, 2025). "In TCGA-PRAD patients, KHDC4 exhibited a significant increase in tumor groups compared to normal groups (p < 0.0001)." (PMID 40560737, 2025). "In this study, profiling analysis of transcriptome datasets between late-stage and early-stage PCa identified KHDC4 as a member of the KH Homology Domain-Containing Protein family with higher expression in prostate tissues, further elevated in tumor groups." (PMID 40560737, 2025). "In this study, the knockdown of KHDC4 supports its role in contributing to tumor growth and motility features in the PCa cell model." (PMID 40560737, 2025). "Based on their related expression, the distribution of KHDC4 was the most highly expressed member and increased in the tumor group (p < 0.0001)." (PMID 40560737, 2025). "Functional assays revealed that KHDC4 knockdown led to a notable reduction in tumor growth rates, as evidenced by colony formation and cell proliferation assays." (PMID 40560737, 2025). "In breast cancer, the expression of KHDC4 is involved in the regulation by miR-641, contributing to tumor malignancy." (PMID 40560737, 2025). "Moreover, KHDC4 depletion significantly impaired tumor cell motility, as demonstrated by wound healing assays." (PMID 40560737, 2025). "Notably, a single-cell level dataset (GSE176031) profiling the distribution of KHDC4 revealed that malignant cell types (highlighted in red boxes) exhibited the highest intensity level (0.4 (log (TPM/10+1))) compared to other major cell lineages in the tumor microenvironment." (PMID 40560737, 2025). "Similar to KHDC4, the distribution of TRAF2 indicated a malignant cell type (highlighted in red) with the highest intensity level compared to other major cell lineages in the PCa tumor microenvironment (GSE176031)." (PMID 40560737, 2025). "Importantly, the correlation between KHDC4 and TRAF2 among different pathologic tumor stages and lymph node metastasis was reflected in the Gleason score evaluation system based on PCa tissue biopsy." (PMID 40560737, 2025). "Moreover, single-cell profiling indicated that although the expression intensity of KHDC4 and TRAF2 in malignant cells was higher than in other clusters or cell types, the differences in the proportion of positive cells may be attributed to distinct tumor cell populations." (PMID 40560737, 2025).
KHDC4 also shares sentences with these, for which no sentence is quoted: oral squamous cell carcinoma (1 paper).